RB1 (RB transcriptional corepressor 1)
Diseases named in the same sentence as RB1 in open-access papers (continued):
Sharing a sentence is not in itself a finding about the gene and the disease.
retinoblastoma (continued). "Moreover, this study claims that beyond RB1, methylation of the tumor suppressor gene RASSF1A which is related to the stability of the microtubules, as well as p16INK4A which encodes a CDK inhibitor that stops the cell cycle, can lead to retinoblastoma." (PMID 41150792, 2025). "Retinoblastoma may initiate from RB1-depleted cone precursors in the human retina." (PMID 41009976, 2025). "However, while RB1 mosaicism has been reported in retinoblastoma, its clinical implications and potential impact on cfDNA testing remain unclear." (PMID 40338593, 2025). "Retinoblastoma (RB) is the most common primary intraocular malignancy in children and mostly initiates with biallelic inactivation of the RB1 gene." (PMID 40463882, 2025). "In addition, patients with retinoma, a benign, non-progressive retinal lesion, who carry germline RB1 mutations (H1) with no full-blown retinoblastoma, still carry a risk for second non-ocular malignancies." (PMID 41009976, 2025). "Retinoblastoma (RB) is a rare pediatric ocular malignancy primarily driven by biallelic inactivation of the RB1 tumor suppressor gene." (PMID 40943594, 2025). "In rare instances, sporadic retinoblastoma may develop without an RB1 mutation, resulting from somatic amplification of the MYCN gene." (PMID 40317918, 2025). "However, the direct role of none of these genes in retinoblastoma is yet fully understood and warrants further investigation for their potential diagnostic or prognostic relevance; nonetheless, they highlight the expanding genetic landscape of retinoblastoma beyond RB1 and MYCN." (PMID 41009976, 2025). "Indeed, siblings to children with retinoblastoma without detected germline RB1 mutation have a low, but not negligible, risk of retinoblastoma and are usually offered eye surveillance in general anesthesia." (PMID 38803632, 2024). "Verification of non-heritable retinoblastoma in patients with unilateral disease requires either the detection of both somatic RB1 pathogenic variants and the exclusion of those variants in a peripheral blood sample or, in very rare cases, the identification of somatic MYCN amplification." (PMID 38672657, 2024). "In our cohort, six patients had unilateral retinoblastoma without germline RB1 variants." (PMID 38803632, 2024). "Recently, it has been reported that the amplification of the MYCN gene may cause the development of retinoblastoma even in the absence of RB1 mutations." (PMID 38540335, 2024). "In rare cases, sporadic retinoblastoma could develop in the absence of RB1 mutation as a consequence of the somatic amplification of the MYCN gene." (PMID 38398694, 2024). "A recent publication has reported the detection of methylation signatures in AH from retinoblastoma patients, suggesting that, in cases where initial somatic RB1 screening fails to identify two pathogenic variants, further methylation testing may be possible." (PMID 38672657, 2024). "This lack of detection of retinoblastoma patients in many low-income countries present a challenge for any future studies in detecting differences in rates of de novo germline pathogenic variants in RB1." (PMID 35361938, 2023). "In conclusion, this comprehensive network-based pharmacological analysis suggests a number of testable speculations on the potential molecular mechanisms of curcumin in the treatment of retinoblastoma and predicts RB1, STAT3, and CDKN2A as potential therapeutic targets." (PMID 35911143, 2022).
retinoblastoma (continued). "While the variant we describe was not identified in population or disease‐specific databases, the breakpoint assay could be used to screen cohorts of RB1‐mutation negative retinoblastoma patients to establish the precise prevalence of the mutation." (PMID 35014072, 2022). "The enrichment of genes associated with MYC-targets might indicate that deregulation of gene expression by MYCN could be an important factor in retinoblastoma development, strengthened by rare retinoblastoma entities in which MYCN amplification substitutes for mutational RB1 inactivation." (PMID 35565295, 2022). "Retinoblastoma (RB) is a childhood cancer of the retina initiated upon biallelic inactivation of the RB1 tumor suppressor gene." (PMID 36173648, 2022). "In a small fraction (1.4% of unilateral retinoblastoma) no RB1 mutation was found, but instead an amplification of the MYCN oncogene could be detected and these tumors showed an aggressive clinical course." (PMID 36497295, 2022). "A report has revealed that many retinoblastoma patients do not have any RB1 exon mutation, and from the point of view of the whole genome, the very few genetic mutations found may not be enough to induce tumorigenesis." (PMID 36175480, 2022). "In addition, transplantation of RB1-null organoids into immune-deficient mice did not result in retinoblastoma formation." (PMID 33718380, 2021). "Less than 2% of unilateral, non-familial retinoblastoma patients may present with fully functional RB1 but instead with a MYCN oncogene mutation." (PMID 34195690, 2021). "This preference for CN-LOH of RB1 in retinoblastoma may reflect the necessity of a gene or genes on 13q to be expressed from two alleles or there may be genes essential to the fitness of the cell type that would be left vulnerable by the presence of a single allele." (PMID 33466343, 2021). "Furthermore, RB1 loss in matured retinal cells did not induce retinoblastoma, validating that tumor initiation is restricted to a specific cell within retinal development." (PMID 33718380, 2021). "Loss of RB1 accompanied by gradual increase in genomic instability in the susceptible retinal cells drives disease progression from non-proliferative retinoma to malignant retinoblastoma." (PMID 34680394, 2021). "Previous reports, including one from our cohort, showed an excess of lipoma in patients with hereditary retinoblastoma compared to nonhereditary survivors, suggesting that germline RB1 mutations may also contribute to benign tumor development." (PMID 33917779, 2021). "Simultaneous expression of MYCNOS with MYCN may be needed to imitate human MYCN-driven retinoblastoma without the loss of RB1 in generating a mouse model." (PMID 33270844, 2020). "We hypothesize that MYCNOS1 maintains the features of retinoblastoma/cone signature or “stemness” previously reported for MYCNOS234 and that loss of MYCNOS1 expression induces neuronal differentiation in MYCN-amplified retinoblastoma without RB1 mutation." (PMID 33270844, 2020). "Retinoblastoma (RB) is a major intraocular cancer occurring in children and is initiated by inactivation of the RB1 tumor suppressor gene in the developing retina." (PMID 31782885, 2020). "Retinoblastoma (RB) is the most frequent pediatric retinal tumor and is initiated by biallelic inactivation of RB1, the first discovered tumor suppressor gene." (PMID 32143590, 2020). "The goal of this study was to investigate the FGFR4 p.Gly388Arg variant that plays role in the progression of cancer and retinal growth and may be an effective candidate variant in the Turkish population in retinoblastoma patients with no RB1 gene mutation." (PMID 33456465, 2020). "Interestingly, it appears that RB1 gene mutation is not the only an event that can initiate retinoblastoma formation." (PMID 32047660, 2020).
retinoblastoma (continued). "MYCN-amplified retinoblastoma without RB1 mutation appears to have histopathological and genetic characteristics similar to those of other MYCN-amplified embryonic tumors, such as neuroblastoma, even though the tumor features a retinoblastoma-associated gene expression profile." (PMID 33270844, 2020). "Just as the cloning of the RB1 gene spurred a change in our understanding of cancer genetics and tumor suppressor genes, so these recent developments have led to an exciting new field with the potential application of specific diagnostics and prognostics for retinoblastoma." (PMID 31835688, 2019). "The aim of this study was to investigate possible candidate genes associated with Rb oncogenesis in retinoblastoma patients without RB1 gene mutations including INDELS and large rearrangements and having normal RB1 promoter methylation and having a heavy family history by using NGS‐based technology." (PMID 31207142, 2019). "The emergence in embryogenesis of a new pathogenic RB1 variant in nonfamilial retinoblastoma may be early, with 100% of cells affected, or late, resulting in somatic mosaicism and less than 1% of cells carrying the pathogenic variant." (PMID 31683923, 2019). "Retinoblastoma (RB, OMIM #180200) is a malignant intraocular tumor occurring in young children, which is caused by mutations in both alleles of the RB1 gene." (PMID 31806026, 2019). "In conclusion, in this study we investigated candidate genes that may trigger Rb oncogenesis in six patients with retinoblastoma or retinoma within three families and who did not have a RB1 gene mutation and abnormal RB1 promoter methylation." (PMID 31207142, 2019). "Recently, it has been found that retinoblastoma may occur even in the presence of non-mutated RB1 genes, due to activity associated with the MYCN oncogene." (PMID 29915458, 2018). "Thus, in conclusion, in our series of 18 MYCN‐amplified retinoblastomas, 12 carry inactivating coding sequence mutations in the RB1 gene and six do not." (PMID 28211617, 2017). "MYCNA has been found in retinoblastomas both with mutated or non-mutated RB1 genes." (PMID 29124525, 2017). "Thus, based on current sensitivity of DNA‐based genetic testing, the presence of a subset of retinoblastoma without a detectable mutation in the RB1 gene is not unexpected." (PMID 28211617, 2017). "Moreover, the coexistence of retinoblastoma and lipoma/liposarcoma was observed in sporadic cases, even though the role of the RB1 gene in their pathogenesis and differentiation process remains still unknown." (PMID 28331547, 2017). "Indeed, several studies identified UHRF1 as a direct target of E2F1 in various cell systems, and genetic disruption of E2f1 or E2f3 in a murine retinoblastoma model was shown to ablate UHRF1 expression in Rb1-knockout retinae that would otherwise exhibit high UHRF1 expression." (PMID 28467809, 2017). "Thus, in families which carry the low-penetrance mutations, a reduced number of carriers develop retinoblastoma rather than the expected rate of >99% which is commonly expected for most RB1 mutations." (PMID 28575107, 2017). "Recent studies have shown that there are cases of unilateral Retinoblastoma that are devoid of Rb mutations and these tumors have distinct histological and genomic landscapes (e.g. high MYCN expression) that facilitate aggressive tumor formation similar to that seen in RB1(−/−) tumors." (PMID 29162051, 2017). "Additionally, this retinoblastoma model provides unique possibilities for fast elucidation of novel drug targets by triple multiplex CRISPR/Cas9 gRNA injections (rb1 + rbl1 + modifier gene) in order to address the clinically unmet need of targeted retinoblastoma therapy." (PMID 27739525, 2016).
retinoblastoma (continued). "As RTS patients have a 30% incidence of OS this was somewhat unexpected, but not without precedence given our previous analysis of Osx-Cre pRbfl/fl animals which also do not develop OS despite the high rate of OS in hereditary retinoblastoma kindreds and the rate of RB1 mutation in conventional OS." (PMID 25859855, 2015). "Moreover, MYCN amplification, a rare feature of most primary human retinoblastomas, occurs with greater incidence in retinoblastomas without RB1 mutations." (PMID 26379276, 2015). "Retinoblastoma (RB, OMIM#180200), the most common pediatric eye tumor in the retina is initiated by inactivating biallelic variants of RB1 gene." (PMID 25928201, 2015). "In addition, a recent study reported that a small subset of human unilateral nonfamilial retinoblastomas (1.5%) with MYCN amplification (≥10 copies) lack RB1 mutations." (PMID 24509483, 2014). "We identifed 10 retinoblastomas in our cohort that lacked RB1 point mutations or indels." (PMID 24509483, 2014). "Retinoblastoma (RB) is a prototype cancer driven in large part by lesions in Rb1, a well-defined genetic element and clinical target." (PMID 24478791, 2014). "We hypothesize that retinoblastomas are predisposed to exhibit CIN because of the absence of RB1 but this is more likely to occur when additional stress, such as oxidative or replicative stress, overwhelms the cellular machinery that maintain genome stability." (PMID 23765217, 2013). "However, SaOS2 and OVCAR3 cell lines show similar miR-24:protein ratios as RB1-/- retinoblastoma cell lines, suggesting that miR-24 regulation of ARF may apply to other cell types." (PMID 22336108, 2012). "Retinoblastoma (RB, OMIM 180200], the most frequent childhood intraocular tumor, is caused by mutations in the RB1 gene." (PMID 22219649, 2011). "Unlike children with germline RB1 mutations, Rb1 mice did not develop retinoblastoma." (PMID 16231976, 2005). "Retinoblastoma is an early-childhood retinal malignancy driven predominantly by biallelic RB1 inactivation and consequent RB-E2F checkpoint deregulation." (PMID 42212122, 2026). "Emerging genes beyond RB1 (e.g., BCOR, CREBBP) highlight the expanding genetic landscape of retinoblastoma." (PMID 41009976, 2025). "In contrast, in the heritable form, a germline RB1 mutation (M1) is present in all body cells with somatic (M2) mutations in multiple retinal cells, increasing the risk of bilateral (80%) and multifocal (67%) retinoblastomas with an early age of onset and secondary non-ocular cancers later in life." (PMID 41009976, 2025). "Genome-wide profiling further reveals dozens of hypermethylated tumor suppressors (e.g., RB1, CDKN2A, RASSF1A, MLH1, etc.), reinforcing the idea of epigenetic cooperativity in retinoblastoma pathogenesis." (PMID 41150792, 2025). "While RB1 remains the primary gene associated with retinoblastoma, and MYCN amplification accounts for a small subset of non-hereditary, unilateral cases, emerging research has identified a number of additional genes that may play a role in retinoblastoma development or progression." (PMID 41009976, 2025). "Finally, these results support consideration of evaluating patients with retinoblastoma undergoing cfDNA testing with persistent RB1 variants in cfDNA but no clinical evidence of disease for RB1 mosaicism to reduce the chance of a false-positive interpretation or overtreatment." (PMID 40338593, 2025). "Notably, in patients with unilateral retinoblastoma and no family history, over 15% of cases may still carry a germline or mosaic RB1 mutation." (PMID 41009976, 2025).
retinoblastoma (continued). "By developing rb1/rbl1 chimeric mutants using CRISPR/Cas9 in Xenopus embryos, researchers rapidly established a retinoblastoma model." (PMID 41210874, 2025). "This entity is described by the classifier as being different from typical RB as it lacks the inactivation of RB1, but shares a CNV of 6p gain a feature of retinoblastoma." (PMID 41353556, 2025). "Overexpression of DNMT1 is associated with hypermethylation of tumor suppressor genes as well as inactivation of other genes and genomic regions that may lead to loss of heterozygosity (LOH) in the other RB1 allele in cases of retinoblastoma when only one of the two alleles was not functional." (PMID 41150792, 2025). "In addition, the identification of heterozygous RB1 variants of unknown significance neither establishes nor rules out the diagnosis of retinoblastoma." (PMID 41009976, 2025). "In conclusion, with proficient RB1, MYCN-induced high level of E2F expression dysregulates the cell cycle and contributes to retinoblastoma carcinogenesis." (PMID 37606819, 2024). "In retinoblastoma, MYCN amplification (MYCNA) occurs in RB1−/−MYCNA retinoblastomas and the rare, RB1-proficient MYCNA retinoblastomas." (PMID 39079981, 2024). "In retinoblastoma, MYCN amplification occurs in both the more common RB1−/− and rare RB1-proficient backgrounds." (PMID 39079981, 2024). "Furthermore, 23% of patients with non-familial unilateral Rb had germline RB1 mutations." (PMID 39234041, 2024). "In the case of cattle, genes like TRPA1, RB1 and SCNN1B are predicted to be involved in respiratory diseases, retinoblastoma and renal diseases, respectively." (PMID 38674383, 2024). "Some of the retinoblastomas with MYCNA have intact RB1 genes (RB1+/+, +/−) with proficient expression of Rb1." (PMID 35729105, 2022). "The present study identifies RB1 and HK1 as previously unrecognized regulators of metabolic adaptation in retinoblastoma cells." (PMID 36291051, 2022). "In total, 5 retinoblastomas displayed high-level MYCN amplification, with 3 being RB1+/+, 1 being RB1+/–, and 1 being RB1–/–." (PMID 36245757, 2022). "We present a new in vivo model of retinoblastoma with MYCNA and wild type RB1 in the chicken embryonic retina that recapitulates the early events that lead to malignant transformation." (PMID 35729105, 2022). "We report that ectopic expression of RB1 reduced mitochondrial respiration and spare respiration capacity of WERI-Rb1, Y79, and patient-derived GL1-RB1 retinoblastoma cells, highlighting that mitochondrial function is curtailed by the wild-type Rb protein." (PMID 36291051, 2022). "Only patients with constitutional RB1 variants that developed retinoblastoma were included in the study, and for this reason, RB1 variants associated with milder phenotypes or without the development of retinoblastoma in each individual might be underrepresented." (PMID 33807189, 2021). "We also revealed a relatively high frequency of asymptomatic carriage of the RB1 mutations among the parents of retinoblastoma patients, highlighting the utmost necessity for molecular analysis among the probands’ relatives irrespective of their clinical status and family history of retinoblastoma." (PMID 34680218, 2021). "Of the non-RB1 gene alterations in our cohort, only MYCN on 2p24.3 and TSC2 on 16p13.3 correspond with common CNVs that characterize retinoblastoma." (PMID 33466343, 2021). "However, retinoblastoma cases exist where mutations in RB1 have not been detected." (PMID 33670346, 2021).